CCDC179 (coiled-coil domain containing 179)
Tractability: No criterion of Open Targets' tractability assessment is met for any kind of drug.
Gene: Protein-coding gene on chromosome 11 (22,846,922 to 22,860,474, reverse strand). Ensembl gene ENSG00000255359.
Gene Ontology:
Molecular function: protein binding
Genetic constraint (gnomAD): Loss-of-function variants: 2 observed, 2.8 expected, observed/expected ratio (o/e) 0.71, 90% interval 0.28 to 1.77. That is too few expected variants to judge how well the gene tolerates losing a copy. Missense variants: 23 observed, 17.41 expected, observed/expected ratio (o/e) 1.32, 90% interval 0.95 to 1.81. Synonymous variants: 5 observed, 6.74 expected, observed/expected ratio (o/e) 0.74, 90% interval 0.39 to 1.52.
Homologues: Orthologues: macaque CCDC179 (96% identical), chimpanzee CCDC179 (93% identical), rabbit CCDC179 (75% identical), dog CCDC179 (63% identical), mouse Ccdc179 (62% identical), rat Ccdc179 (62% identical), guinea pig CCDC179 (57% identical), pig CCDC179 (57% identical).